CDC25C (cell division cycle 25C)
Description:
Functions as a dosage-dependent inducer in mitotic control. Tyrosine protein phosphatase required for progression of the cell cycle. When phosphorylated, highly effective in activating G2 cells into prophase. Directly dephosphorylates CDK1 and activates its kinase activity.
Synonyms: PPP1R60; CDC25
Tractability: Small molecule: a structure with a bound ligand is known; a high-quality ligand is known; it belongs to a druggable protein family. PROTAC: ubiquitination databases record sites on it; a small molecule that binds it is known.
Target class: Phosphatase; Serine/threonine/tyrosine protein phosphatase; Enzyme; Protein Phosphatase
Chemical probes: NSC 95397
Gene: Protein-coding gene on chromosome 5 (138,285,251 to 138,338,355, reverse strand). Ensembl gene ENSG00000158402.
Subcellular location: Nucleus
Subcellular location (Human Protein Atlas): Nuclear speckles
Pathways (Reactome):
Cell Cycle: Activation of ATR in response to replication stress; Chk1/Chk2(Cds1) mediated inactivation of Cyclin B:Cdk1 complex; Cyclin A/B1/B2 associated events during G2/M transition; Polo-like kinase mediated events
Disease: Deregulated CDK5 triggers multiple neurodegenerative pathways in Alzheimer's disease models
Signal Transduction: RHO GTPases activate PKNs
Gene Ontology:
Molecular function: protein binding; protein kinase binding; protein serine/threonine kinase binding; WW domain binding; phosphoprotein phosphatase activity; protein tyrosine phosphatase activity
Biological process: G2/M transition of mitotic cell cycle; cell population proliferation; positive regulation of G2/M transition of mitotic cell cycle; positive regulation of G2/MI transition of meiotic cell cycle; regulation of cyclin-dependent protein serine/threonine kinase activity; regulation of mitotic nuclear division; positive regulation of cell cycle G2/M phase transition
Cellular component: nuclear speck; nucleus; cytoplasm; cytosol; nucleoplasm; mitochondrial intermembrane space
Genetic constraint (gnomAD): Loss-of-function variants: 26 observed, 30.71 expected, observed/expected ratio (o/e) 0.85, 90% interval 0.62 to 1.17. The upper end of that interval is the gene's LOEUF score, 1.17, which puts it in group 5 of 6, group 1 being the genes least tolerant of losing a copy. Missense variants: 346 observed, 388.74 expected, observed/expected ratio (o/e) 0.89, 90% interval 0.81 to 0.97. Synonymous variants: 126 observed, 147.72 expected, observed/expected ratio (o/e) 0.85, 90% interval 0.74 to 0.99.
Homologues: Orthologues: macaque CDC25C (96% identical), chimpanzee CDC25C (86% identical), pig CDC25C (80% identical), dog CDC25C (80% identical), rabbit CDC25C (77% identical), rat Cdc25c (64% identical), mouse Cdc25c (62% identical), tropical clawed frog cdc25c (47% identical), Caenorhabditis elegans cdc-25.2 (19% identical), Caenorhabditis elegans cdc-25.3 (18% identical). Paralogues in human: CDC25B (36% identical), CDC25A (36% identical).
Diseases named in the same sentence as CDC25C in open-access papers:
CDC25C is named in the same sentence as 89 diseases in open-access papers, as found by Europe PMC text mining. Sharing a sentence is not in itself a finding about the gene and the disease. The quoted sentences say what the papers report.
breast carcinoma (45 papers, 2013 to 2025). "PKMYT1, KIF4A, and CDC25C were associated with GO in terms of BPs; previous studies also revealed the overexpression of these genes in breast cancer." (PMID 34834441, 2021). "AURKA and PLK1 are essential mitotic regulators that promote the G2/M transition and are often overexpressed in aggressive breast cancers, while CDC25C facilitates CDK1 activation and has been associated with unchecked cell cycle progression in high-grade tumors." (PMID 41017855, 2025). "In breast cancers, ZER caused G2/M phase cell cycle arrest associated with downregulation of cyclin B1, Ddk1, Cdc25C, and Cdc25B and Bax/Bak-mediated apoptosis in human breast cancer (MDA-MB-231 and MCF-7) cells and retarded growth of MDA-MB-231 xenografts in vivo." (PMID 25025076, 2014). "Our experiment data further verified that LAS reduced PLK1 mRNA and protein expression in breast cancer, accompanied by downregulating CDC25C and AKT phosphorylation." (PMID 38495493, 2024). "Our experimental data further verified that NF113 reduced GADD5A mRNA and protein expression, which were significantly upregulated in breast cancer, with downstream CDC25C and AKT phosphorylation changes." (PMID 39458909, 2024). "In our previous study, we demonstrated the inhibition of miR-142-3p on breast cancer cell cycle by targeting CDC25C." (PMID 37403081, 2023). "The expression level of CDC25C increased in ovarian tumor and breast cancer cells, which are mainly composed of diploid tumor cells." (PMID 32393310, 2020). "For breast cancer, the differences of CDC25C (P = 0.001), CDK1 (P = 0.000), CHK1 (P = 0.001), CHK2 (P = 0.000), PLK1 (P = 0.000) and Aurora A (P = 0.000) expression between primary cancer with and without metastasis also had statistical differences." (PMID 32393310, 2020). "Among them, phosphatases PTP1B in blood cells 93T and Cdc25C in breast cancer cells have been reported to be subjected to S-sulfhydration." (PMID 31963573, 2020). "IHC staining confirmed that CDC25C expression level was closely related to the grade and stage in human ovarian tumors and breast cancer." (PMID 32393310, 2020). "Our results demonstrate that TAIII activates both ATM and p38 MAPK pathways, then inhibits Cdc25C level, inducing G2/M phase arrest in breast cancer cells." (PMID 33628174, 2020). "Recently, one research group identified that diosgenin promoted apoptosis and triggered cell cycle arrest at the G2/M phase through regulation of Chk1 kinase, Cdc25c pathway, and Bcl-2 in breast cancer cells." (PMID 32626765, 2020). "Taken together, these findings reveal that the anti-proliferative activity of diosgenin involves the induction of G2/M phase arrest via modulating the Cdc25C-Cdc2-cyclin B pathway and mitochondria-mediated apoptosis in human breast cancer cell lines." (PMID 31881805, 2019). "Three exons with little or no expression in NBS were called as +1 in all three tumor classes, indicating higher expression of full length CDC25C in breast cancer." (PMID 28717182, 2017). "FKA induces G2M arrest in cell cycle progression of HER2-overexpressing breast cancer cell lines through inhibition of Cdc2 and Cdc25C phosphorylation and downregulation of expression of Myt1 and Wee1 leading to increased Cdc2 kinase activities." (PMID 28335434, 2017). "Although the upregulated CDC25A and CDC25B isoforms are commonly reported in breast carcinoma, CDC25C is another, less recognized oncogenic isoform." (PMID 27801830, 2016). "Considering the possible underrated measurement of CDC25C expression in most studies and the prospective involvement of CDC25C in female cancers, we focus our priorities on CDC25C in the carcinogenesis of breast cancer." (PMID 27801830, 2016).
breast carcinoma (continued). "In our previous study, miR-142-3p was identified as a tumor suppressor, which could inhibit breast cancer proliferation and led to G2/M arrest of cell cycle by regulation of CDC25C." (PMID 37403081, 2023). "Similarly, in pancreatic adenocarcinoma and in breast cancer, high CDC25C mRNA levels indicated bad prognosis." (PMID 36830899, 2023). "These analytical data suggest that NEK2 may be involved in the recurrence of Basal-, LumA- and LumB-subtype breast cancer, while NEIL3 and CDC25C may only be involved in recurrence of LumA-subtype breast cancer." (PMID 33644115, 2021). "CDC25C (cell division cycle 25C) may be a potential target for aspirin for inhibiting the proliferation of human breast cancer cells, and its gene function is mainly enriched in cell cycle and cell division." (PMID 33644115, 2021). "Thus, in this study, we aim to delineate the phosphorylation of CHK2 and CDC25C in breast cancer using immunohistochemistry, as well as expound the role of these proteins in breast cancer development." (PMID 27801830, 2016). "Here, our results demonstrate that SL4 was able to induce cell cycle arrest at the G2/M phase in breast cancer cells by activating the MAPK pathway and subsequently regulating cell cycle-associated proteins, including p21, cdc25C, cdc2, cyclin B1 and cyclin A2." (PMID 27819344, 2016). "However, few studies correlated the phosphorylation of CHK2 and CDC25C with breast cancer." (PMID 27801830, 2016). "In addition, CDC25C may be related to the breast cancer due to the potential roles of CDC25C and pCDC25C (Ser216) in certain cancer pathways in women (e.g., vulvar carcinomas)." (PMID 27801830, 2016). "For example, in human breast cancer cells, quercetin inhibits lapatinib-sensitive and -resistant breast cancer cell growth by modifying levels of factors that regulate cell cycle G2/M progression and apoptosis, such as cyclin B1, p-Cdc25c (Ser216), Chk1, caspase 3, caspase 7, and PARP." (PMID 27827912, 2016). "We identified several DEGs involved in the cell cycle, including CDK1, CHEK1, CDC25C, BUB1, CDC20, and TTK, which not only are related to breast cancer patient survival but also have existing targeted drugs." (PMID 38166892, 2024). "Here, we found that low expression of NEIL3, CDC25C, and NEK2 predicted high RFS and OS respectively (p < 0.05), and low expression of HCN2 predicted high OS (p < 0.05) in all breast cancer." (PMID 33644115, 2021). "MiR-142-3p suppresses growth of colorectal cancer and breast cancer cells by targeting CDK4, Beach-1, and CDC25C." (PMID 33396321, 2020). "Also, a study on breast cancer cells (MDA-MB-231 and MCF-7) showed that Zerumbone could lead to G2/M phase cell cycle arrest associated with Bax/Bak-mediated apoptosis and downregulation of cyclin B1, Ddk1, Cdc25C, and Cdc25B." (PMID 32454937, 2020). "Our results showed that TAIII activated the DDR pathway (ATM/Chk2/Cdc25C) and γ-H2AX quickly, indicating that TAIII induces DNA damage in breast cancer cells." (PMID 33628174, 2020).
breast carcinoma (continued). "Breast cancer cells irradiated in the presence of genistein show increased DNA damage and cell cycle inhibition at G2/M phase via activation of ATM, Chk2, Cdc25C and Cdc2 checkpoint pathway." (PMID 31618928, 2019). "Higher expression of CDC25C, ERCC6L or RAD51 was related to shorter overall survival in breast cancer or specified ER-positive breast cancer (all P < 0.05)." (PMID 31506496, 2019). "The elevated ratio of CDC25C C5/C1 detected in our TF-1 SRSF2-P95 mutants, has also been reported to be induced in breast cancer cells by treatment with sublethal doses of DNA-damaging agents, such as cisplatin (CIS) and doxorubicin." (PMID 27552991, 2016). "According to the existing literature, except for NEK2 the expression and prognostic significance of the NEIL3, CDC25C, and HCN2 genes are still unknown in breast cancer." (PMID 33644115, 2021). "More so, the expression of phosphorylation CDC25C was modulated, which may lead to G2/M arrest of CTD-treated cells, which is in line with previous breast cancer reports." (PMID 33785035, 2021). "Moreover, in breast cancer patients, high FHL1 expression positively correlated with cytoplasmic CDC25C accumulation and negatively correlated with nuclear CDC25C accumulation." (PMID 28094252, 2017). "We found that proteins expression of CDC25C and p-AKT(T308) were significantly decreased in SK-BR-3 and MDA-MB-231 cells treated with LAS (1,3 μM) compared to that of controls, suggesting that LAS inhibited the phosphorylation of CDC25C and AKT via regulating PLK1 pathway in breast cancer cells." (PMID 38495493, 2024). "In all breast cancer, low expression of NEIL3, CDC25C and NEK2 predicted high RFS (p < 0.05) respectively, while high expression of HCN2 predicted high RFS (p < 0.05), and low expression of NEIL3, CDC25C, NEK2 and HCN2 predicted high OS respectively (p < 0.05)." (PMID 33644115, 2021). "The exact roles of CHK2 and CDC25C in breast cancer have not been fully elucidated." (PMID 27801830, 2016). "Indeed, RPPA data revealed an enrichment of cell cycle‐related genes including CDC25C and PLK1 in proteins downregulated by metformin, echoing a previous report showing selective translational inhibition of cell cycle regulators such as cyclin E2 and ODC1 by metformin in breast cancer cells." (PMID 30221473, 2018).
colon carcinoma (21 papers, 2012 to 2025). "Curcumin inhibited the gene expression of Cdc25c, CDK1, and cyclin B1 and promoted the gene expression of Wee1 in colon cancer cells, causing cell cycle arrest at the G2/M phase." (PMID 33233354, 2020). "Induction of G2/M arrest by TAX and NOC with increases in phosphorylated Cdc25C and cyclin B1 protein were observed in human colon cancer cells." (PMID 31906029, 2019). "Rosuvastatin decreased Cdc25c protein expression in colon tumors, whereas DFMO resulted in increasing Cdc25c protein expression and the combination of DFMO and Rosuvastatin increased Cdc25c protein expression compared to control colon tumors." (PMID 27841323, 2016). "Significant increases in the G2/M ratio and cyclinB1/cdc25c protein expression by EVO were respectively identified in colon carcinoma cells via a flow cytometric analysis and Western blotting." (PMID 24959718, 2014). "Addition of the JNK inhibitor, SP600125, decreased EVO-induced G2/M arrest and cyclinB1/cdc25c protein expression in both colon carcinoma cell lines." (PMID 24959718, 2014). "For example, increased expression of Cdc25C has been reported in a fraction of colon cancer cells, endometrial cancer and prostate carcinomas." (PMID 23637932, 2013). "We found that GSC treatment resulted in downregulation of Cdc25c and cyclin B1 expression in HT-29 colon cancer cells." (PMID 22474493, 2012). "Similar phenomenon were reported that reducing cyclin A/CDK2 and Cdc25C expressions lead to S phase arrest in human Lovo colon cancer cells." (PMID 22300067, 2012). "The CDC25C gene was identified as one of the key genes in both the prediction of colon adenocarcinoma by anchorage-dependent cell death-related genes as well as in prognostic models of colon cancer." (PMID 39963131, 2025). "Meanwhile, the downregulation of CDC25C by curcumin promotes anti-proliferation in colon cancer." (PMID 34366863, 2021). "Among the 14 model genes, the expression levels of FZD3, CDC25C, CDCA2, NEBL, and HMMR were positively correlated with better prognosis of colon cancer." (PMID 41425852, 2025). "Specifically, CDC25C, ANKRD22, SEZ6L2, SERPINA1, and NOS2 were overexpressed in colon cancer tissues compared with normal tissues." (PMID 41425595, 2025). "This study revealed that remimazolam promoted the cell-cycle progression and proliferation of HCT8 colon cancer cells by upregulating CDK1, PTTG1, CDC25C, CDK4, PLK1, PCNA, Ki67, RNASEH2B, FEN1, Cyclin D1,CD44 CDK2, CDKN3, CDC45, IQGAP3, and CDK6." (PMID 38725628, 2024). "The effect of DADS has also been reported to induce ROS in human colon cancer COLO 205 and A549 lung cancer cells through the upregulation of cyclin B, cdc25c-se-216-9, and Wee1." (PMID 35213970, 2022). "Previous report indicated that a novel aroylthiourea analogue-induced proliferation inhibition of human colon cancer HCT116 cells and G2/M phase arrest is involved in activation of Chk1 and inactivation of Cdc25C." (PMID 26147394, 2015). "In colon cancer cells, initial reduction in ERK signaling by BRAFV600E inhibitor treatment decreases the phosphatase activity of CDC25C, which in turn results in elevated EGFR phosphorylation." (PMID 26023796, 2015). "Therefore, CDC25C and P4HA1 have the potential to serve as biomarkers for COAD patients and contribute to the decision-making process regarding colon cancer treatment." (PMID 36273131, 2022).